TMEM169 (transmembrane protein 169)
Synonyms: FLJ34263
Tractability: Antibody: UniProt predicts a signal peptide or a membrane-spanning region. PROTAC: ubiquitination databases record sites on it.
Gene: Protein-coding gene on chromosome 2 (216,081,866 to 216,102,783, forward strand). Ensembl gene ENSG00000163449.
Subcellular location: Membrane
Subcellular location (Human Protein Atlas): Focal adhesion sites
Gene Ontology:
Cellular component: membrane
Genetic constraint (gnomAD): Loss-of-function variants: 18 observed, 28.93 expected, observed/expected ratio (o/e) 0.62, 90% interval 0.43 to 0.92. The upper end of that interval is the gene's LOEUF score, 0.92, which puts it in group 3 of 6, group 1 being the genes least tolerant of losing a copy. Missense variants: 320 observed, 388.31 expected, observed/expected ratio (o/e) 0.82, 90% interval 0.75 to 0.9. Synonymous variants: 136 observed, 150.29 expected, observed/expected ratio (o/e) 0.9, 90% interval 0.79 to 1.04.
Homologues: Orthologues: chimpanzee TMEM169 (99% identical), macaque TMEM169 (97% identical), dog TMEM169 (92% identical), guinea pig TMEM169 (90% identical), pig TMEM169 (89% identical), mouse Tmem169 (88% identical), rabbit TMEM169 (88% identical), zebrafish tmem169b (55% identical), zebrafish tmem169a (49% identical), Drosophila melanogaster CG4596 (32% identical).
Diseases named in the same sentence as TMEM169 in open-access papers:
TMEM169 is named in the same sentence as 4 diseases in open-access papers, as found by Europe PMC text mining. Sharing a sentence is not in itself a finding about the gene and the disease. The quoted sentences say what the papers report.
lung carcinoma (1 paper, 2024). "Therefore, we chose top two of previously unreported potential aging genes (GPCPD1 and TMEM169) to test whether they deregulated in neuroblastoma cell line SH-SY5Y and lung cancer cell line A549 during cell senescence." (PMID 39713269, 2024).
cancer (1 paper, 2025). A tumor composed of atypical neoplastic, often pleomorphic cells that invade other tissues. "Across 33 TCGA tumor types, the pan-cancer co-expression analysis identified three transcripts—IL1RAPL1, KCNK9, and TMEM169—that consistently tracked with OPCML." (PMID 41561740, 2025).
TMEM169 also shares sentences with these, for which no sentence is quoted: neuroblastoma (1 paper); tumor (1).